HLA-DRB1 (major histocompatibility complex, class II, DR beta 1)
Diseases named in the same sentence as HLA-DRB1 in open-access papers (continued):
Sharing a sentence is not in itself a finding about the gene and the disease.
periodontitis (16 papers, 2012 to 2025). An acute or chronic inflammatory process that affects the tissues that surround and support the teeth. "Periodontal diseases are typically associated with the DQ locus, and in a study involving Brazilians, the HLA-DRB1* locus was linked to resistance to periodontitis." (PMID 40283738, 2025). "As regards the pathogenetic factors shared by periodontitis and thyroid disease, 4/5 records focus on hypothyroidism, which is associated with an increased frequency of HLA-DRB1*03 and *04, increased oral biodiversity, and overexpression of specific genes." (PMID 39063437, 2024). "The HLA-DRB1*15:01 allele has been linked to early-onset periodontitis, with the hypothesis that patients with this allele may have an accelerated T-cell response to periodontal pathogens, such as Porphyromonas gingivalis, triggering hyperimmune reactions." (PMID 40283738, 2025). "Frequencies of HLA-A9 and -B15, HLA-DQA1*03:01, HLA-DQB1*03:02 and HLADQB1*03:05 alleles, as well as that of the HLA-DRB1*04:01 allele, were significantly higher in patients with aggressive periodontitis compared with control subjects among Caucasians and Iranian patients." (PMID 32515416, 2020). "Thus far, cigarette smoking and infectious agents causing periodontitis are clearly two environmental agents with the strongest evidence for interaction with genes (HLA-DRB1*SE) in the pathogenesis of RA." (PMID 27629582, 2016). "Thus, variations in HLA-DRB1 and other class II alleles may contribute to a dysregulated immune response, potentially leading to more severe forms of periodontitis." (PMID 40283738, 2025). "However, unlike other loci, such as HLA-DQA1* and HLA-DQB1*, which did not display significant associations with the severity or extent of periodontitis in the sample, this work identified an interesting pattern connected to two alleles of the HLA-DRB1 locus: HLA-DRB1*03 and HLA-DRB1*15." (PMID 40283738, 2025). "Specifically, the study identified the HLA-DRB1*03 and HLA-DRB1*15 haplogroups as being linked to severe and generalized periodontitis." (PMID 40283738, 2025). "This study aims to fill this gap by investigating the association of class II HLA alleles (HLA-DRB1, HLA-DQA1, and HLA-DQB1) with the severity and extent of periodontitis in Brazilian patients with T1D." (PMID 40283738, 2025). "As reported in one of the included studies, cases of periodontitis and presence of HLA-DRB1 expression result in aggravation and a possible development of RA." (PMID 31316593, 2019). "It is important to emphasize that the potential biological effects of the HLA-DRB1*03 and HLA-DRB1*15 polymorphisms in the pathogenesis of periodontitis may be primarily due to their role in the regulation of immune responses." (PMID 40283738, 2025). "Given their roles in immune activation and leukocyte recruitment, HLA-DRB1 and CCR1 emerge as potential biomarker candidates for detection, risk stratification, and therapeutic monitoring in periodontitis, necessitating validation in larger, well-characterized cohorts." (PMID 41347541, 2025). "The statistical analysis revealed that the frequencies of the HLA-DRB1*03 and *04 alleles were significantly increased in hypothyroid patients with or without periodontitis compared with healthy controls." (PMID 39063437, 2024). "In RA patients with no, moderate, or severe periodontitis, 58%, 66%, and 62%, respectively, were positive for HLA-DRB1-SE, and 29%, 21%, and 15%, respectively, had two alleles." (PMID 23075462, 2012). "The primary findings of this study suggest that patients with T1D from a mixed-race Brazilian population who possess the HLA-DRB1*03 or HLA-DRB1*15 haplogroups have a higher risk of developing severe and generalized periodontitis, confirming the hypothesis of this research." (PMID 40283738, 2025).
periodontitis (continued). "Future studies should focus on understanding how carriers of these specific HLA-DRB1 alleles may exhibit increased production of pro-inflammatory cytokines, including TNF-α, IL-1β, and IL-6, all of which are central to the tissue destruction seen in periodontitis." (PMID 40283738, 2025).
ulcerative colitis (16 papers, 2013 to 2026). An inflammatory bowel disease involving the mucosal surface of the large intestine and rectum. "Regarding ulcerative colitis, HLA-DRB1*15:03 is shown to be a risk allele for African American population, whereas HLA-DRB1*15:01, is a risk allele in Caucasian populations, where it is more frequent." (PMID 39355248, 2024). "High-density SNV typing of the HLA region in > 32,000 individuals with IBD implicated several HLA alleles, with the greatest effect size associated with HLA-DRB1*01:03 in both CD and ulcerative colitis." (PMID 38421405, 2024). "Of note, HLA-DRB1*07:01 had previously been implicated in two main inflammatory bowel diseases: Crohn’s disease (CD) and ulcerative colitis (UC)." (PMID 32776973, 2020). "Major histocompatibility complex, class II, DR beta 1 (HLA-DRB1) has been demonstrated to be associated with ulcerative colitis and Crohn's disease." (PMID 30186855, 2018). "Multiple HLA alleles have been associated with IBD, for example, HLA-DRB1*01:03, or with one of IBD’s subsets, i.e., Crohn’s disease (CD) and ulcerative colitis (UC), such as HLA-DRB1*07:01, which is strongly associated with CD and HLA-DRB1*15:01 with UC." (PMID 41514338, 2026). "For example, HLA-DRB1*03 and HLA-DRB1*04, both previously associated with LADA, also confer an increased risk for ulcerative colitis (OR = 3.6) and Crohn’s disease (OR = 3.9), respectively." (PMID 35008256, 2021). "The SNP at the HLA-DRB1/HLA-DRB5 locus associated with ΔHRex in females was also significantly associated with inflammatory bowel disease and ulcerative colitis." (PMID 29769521, 2018). "Genomic DNAs were obtained from a cohort of n = 383 subjects recruited as part of an Ulcerative Colitis study and analyzed for HLA-DRB1." (PMID 23555798, 2013). "HLA-DRB1*13:01 was the top signal for age at diagnosis of ulcerative colitis (3·50 × 10−09)." (PMID 26490195, 2016).
breast carcinoma (15 papers, 2009 to 2026). "This study aims to systematically evaluate the relationship between HLA-DRB1 gene polymorphism and breast cancer." (PMID 33761666, 2021). "At present, the association between HLA-DRB1 allele polymorphism and breast cancer has attracted many scholars’ attention." (PMID 33761666, 2021). "By studying the association of HLA-DRB1 and breast cancer, it is helpful for early diagnosis, early treatment, and prognosis of breast cancer." (PMID 33761666, 2021). "The retrieval objects were observational studies on the relationship between HLA-DRB1 gene polymorphism and breast cancer (including case--control studies, cross-sectional studies, and cohort studies)." (PMID 33761666, 2021). "At present, there have been studies on the correlation between HLA-DRB1 gene polymorphism and breast cancer." (PMID 33761666, 2021). "This study will systematically evaluate the relationship between HLA-DRB1 gene polymorphism and breast cancer based on existing studies." (PMID 33761666, 2021). "In various populations, two alleles of the HLA gene, namely HLA-DRB1*11 and HLA-DRB1*12, have been associated either with protection against breast carcinogenesis or with a risk of breast cancer." (PMID 34712820, 2021). "This study explored the frequency of HLA-DRB1*11 and 1*12 alleles and their involvement in breast cancer." (PMID 34712820, 2021). "This study will explore the early warning signal of breast cancer genetic susceptibility, and provide evidence-based medical evidence for clarifying the role of HLA-DRB1 gene polymorphism in breast cancer." (PMID 33761666, 2021). "This study will explore the relationship between HLA-DRB1 gene polymorphism and breast cancer by systematic review and meta-analysis." (PMID 33761666, 2021). "Previous studies demonstrated the role of the HLA-DRB1 locus in genetic susceptibility to colorectal carcinoma, cervical cancer, acute leukemia, melanoma, renal cell carcinoma, and breast cancer." (PMID 31727096, 2019). "Similarly, in Mexico, a Latino population study associated the HLA-DRB1*1602 allele with breast cancer." (PMID 34712820, 2021). "Therefore, we adopted the meta-analysis method to comprehensively analyze the existing data in order to provide evidence-based medicine evidence for clarifying the relationship between HLA-DRB1 allele polymorphism and breast cancer genetic susceptibility." (PMID 33761666, 2021). "In addition, the deletion of the HLA-DRB1*11 allele is associated (beneficial effect) with obesity/overweight (OR = 0.13; 95% CI [0.01–1.14]; and p = 0.03) which is a risk for breast cancer." (PMID 34712820, 2021). "Several other studies conducted in humans have also showed that some HLA-DRB1 genotypes may increase or decrease the risk of breast cancer." (PMID 31727096, 2019). "As an immune effector molecule, HLA-DRB1 plays an important role in the occurrence and development of breast cancer." (PMID 41560039, 2026). "No risk was found between both family history of breast cancer and carriage of the HLA-DRB1*11 and DRB1*12 alleles between cases and controls in this study." (PMID 34712820, 2021). "No direct association was found between the carriage of HLA-DRB1*11 and 1*12 alleles and breast cancer risk." (PMID 34712820, 2021). "Also, Iran authors found a negative association between the alleles, HLA-DRB1*1301 and HLA-DRB1*0101, and breast cancer, while they found positive associations between the allele HLA-DQA1*0301 and this cancer." (PMID 34712820, 2021). "Also, in Italy, HLA-DRB1*11:01 and HLA-DRB1*10:01 alleles were associated with breast cancer risk." (PMID 34712820, 2021). "This study found no direct association between the carriage of the HLA-DRB1*11 and HLA-DRB1*12 alleles and the occurrence of breast cancer." (PMID 34712820, 2021). "In addition, other studies of Arabs in Tunisia and Turkey have not found any risk related to the carriage of HLA-DRB1*11 and HLA-DRB1*12 alleles and breast cancer." (PMID 34712820, 2021).
Crohn disease (15 papers, 2006 to 2026). A gastrointestinal disorder characterized by chronic inflammation involving all layers of the intestinal wall, noncaseating granulomas affecting the intestinal wall and regional lymph nodes, and transmural fibrosis. "In terms of genetics, MHC class II genes, especially the HLA-DR1 and DR4 subtypes, are associated with RA sensitivity, and HLA-DRB1 is associated with Crohn's disease sensitivity." (PMID 17078892, 2006). "For example, certain HLA alleles, such as HLA-DQ2 and HLA-DQ8, are more prevalent in populations of European descent and are strongly associated with celiac disease, while others, like HLA-DRB1*01, are more common in East Asian populations and are linked to diseases like Crohn’s disease." (PMID 40806407, 2025). "Rather the T1DM-Chrohn’s association is driven by different genes sharing common pathways such as CTLA4 and INS, or HLA-DRB1 with genes others than itself, which are genes of the HLA complex genes associated with both T1DM and Crohn’s disease." (PMID 31072055, 2019). "In this context, Braak’s hypothesis connects the onset of PD to the alleles HLA-DRB1*15:01, -DRB1*04:02:01, -DQA1*03, and -DQB1*03:02:01 that are associated with Crohn’s disease, colitis or celiac disease, and that we found were significant (p<0.05) in the PPMI cohort." (PMID 38590523, 2024).
melanoma (15 papers, 2004 to 2025). A malignant, usually aggressive tumor composed of atypical, neoplastic melanocytes. "Concerning HLA-DRB1, this marker plays an important role in immune antigen presentation and its overexpression has been correlated with increased risk of melanoma recurrence." (PMID 37047539, 2023). "The alleles that differed among melanoma patients were HLA-A*03, HLA-B*037, *53, *54, *58, *59, *78, HLA-DRB1*1102, HLA-DQB1*0201, and *0302 with corresponding P values .042.033.050.046.001.021.004.021.006 and .033, respectively." (PMID 20549830, 2010). "It has been reported that HLA phenotypes other than HLA-DRB1*04 occur in association with melanoma in various white national or ethnic groups." (PMID 15310399, 2004). "This conclusion is consistent with previous studies in which HLA-DRB1*04 was associated with melanoma, because HLA-DQB1*0301 is in linkage disequilibrium with HLA-DRB1*04." (PMID 15310399, 2004). "And the down-regulation expression of HLA-DRB1 in melanoma tissues is not only associated with metastasis and poor prognosis in CM patients, but also may accelerate the transition of TME from tumor suppressive to tumor friendly." (PMID 36129956, 2022). "A recent study discovered dietary l-fucose increased anti-tumor immunity and enhanced immune checkpoint blockade responses in melanoma by inducing fucosylation and enrichment of HLA-DRB1 in a mouse model." (PMID 40821120, 2025). "Meanwhile, fucosylation of HLA-DRB1 enhanced the anti-tumor effect by recruiting cytotoxic T cells in melanoma." (PMID 37612293, 2023). "This technique, lectin-mediated PLA (L-PLA), revealed cytoplasmic and/or membranous localization of endogenous fucosylated HLA-DRB1 in melanoma cells that is lost upon FUTi treatment, confirming l-fuc-stimulated cell surface localization of HLA-DRB1." (PMID 36690875, 2023). "In conclusion, fucosylation of HLA-DRB1 is a key regulator of itIC abundance in melanomas, and this mechanism, together with fucosylation-regulated CD4+ T cell biology, can be therapeutically exploited using oral l-fuc administration." (PMID 36690875, 2023). "We assessed potential associations between tumor fucosylation, total/fucosylated HLA-DRB1, CD4+ T cells and responder status in expanded cohorts of patients with melanoma treated with anti-PD1 therapy." (PMID 36690875, 2023). "And the result of the representative immunohistochemical images of HLA-DRB1 in normal skin tissue and melanoma tissue from The Human Protein Atlas (HPA) database were in accordance with the gene expression box plots." (PMID 36129956, 2022). "The GEPIA webserver was applied to validate the expression level of HLA-DRB1 in the melanoma (461 tumor samples from the TCGA database) and the matching normal (558 normal skin samples from the GTEx database) samples." (PMID 36129956, 2022). "The GEPIA web server and the representative immunohistochemical images of HLA-DRB1 in the normal skin tissue and melanoma tissue from the Human Protein Atlas (HPA) database were applied to validate the expression level of HLA-DRB1." (PMID 36129956, 2022). "In the next step we analyzed peripheral blood cells from HLA-DRB1*03+ melanoma patients and HLA-DRB1*0301+ normal donors for the presence of TRP-164–78- and TRP-1284–298-specific CD4+ T cells." (PMID 21152437, 2010). "Our screening approach identified new HLA-DRB1*0301-restricted CD4+ T cell epitopes derived from melanoma antigens." (PMID 21152437, 2010). "Among the melanoma cell lines tested we found that Ma-Mel-108 cells expressing both, HLA-DRB1*0301 and TRP-1, were recognized." (PMID 21152437, 2010). "Based on this result we screened PBMC from six HLA-DRB1*03+ melanoma patients (GA, ME, PK, VHP, SA, BH) and four HLA-DRB1*0301+ healthy donors (BF1, BF3, BF4, BF5) for the presence of peptide #19-reactive T cells." (PMID 21152437, 2010).
melanoma (continued). "Abrogation of l-fuc-induced itIC and tumor growth suppression by EB1 knockdown was rescued by reconstitution with only WT but not glycofucomutant EB1, demonstrating that glycosylation–fucosylation of EB1 or HLA-DRB1 is essential for l-fuc-triggered itIC induction and melanoma suppression." (PMID 36690875, 2023). "Melanoma fucosylation and fucosylated HLA-DRB1 associate with intratumoral T cell abundance and anti-programmed cell death protein 1 (PD1) responder status in patient melanoma specimens, suggesting the potential use of melanoma fucosylation as a strategy for stratifying patients for immunotherapies." (PMID 36690875, 2023). "However, results are inconsistent, with some suggesting HLA-DRB1 to be positively correlated with the survival, prognosis and tumor microenvironment remodeling of melanoma patients." (PMID 37047539, 2023). "Thus, despite the other fucosylated proteins identified in melanoma cells, these data confirm that the N48 glycosylation–fucosylation of HLA-DRB1 is a key regulator of anti-melanoma immunity and tumor suppression." (PMID 36690875, 2023). "Elucidation of the mechanistic determinants is expected to advance our understanding of the immunobiology of melanoma and other cancers and to inform efforts in implementing fucosylation and/or fucosylated HLA-DRB1 as biomarkers and of l-fuc as a therapeutic agent." (PMID 36690875, 2023). "Moreover, the correlation analysis between the Stage of patients and the HLA-DRB1 expression showed that the expression level of HLA-DRB1 decreased with the progression of melanoma." (PMID 36129956, 2022). "However, we still believe that the expression level of HLA-DRB1 has the ability to accurately predict the prognosis of melanoma patients, which provides a new idea for the treatment of CM." (PMID 36129956, 2022). "Similarly, genes related to melanoma invasion were downregulated in SIRT2-deficient melanoma cell lines (e.g., HLA-DRA, IL-6, CD74, and HLA-DRB1 in the SSW30 clone, Dataset S1; PTPRZ1, FST, and NRCAM in the SSM15 clone, Dataset S2)." (PMID 31091806, 2019). "Therefore, it can be inferred that the down-regulation of HLA-DRB1 in CM patients may be a mechanism of immune escape of melanoma cells." (PMID 36129956, 2022). "Specifically, fucosylation regulates the cell surface abundance of HLA-DRB1, which triggers robust CD4+ T cell-mediated itIC induction and melanoma suppression." (PMID 36690875, 2023). "And the validation of the expression level of HLA-DRB1 based on the GEPIA web server and the HPA database showed that the expression level of HLA-DRB1 in the melanoma tissue was higher than that in normal skin tissue." (PMID 36129956, 2022). "Correlation analysis and survival analysis showed that the expression level of HLA-DRB1 was negatively correlated with the Stage of the patients while positively correlated with the survival, prognosis and TME of melanoma." (PMID 36129956, 2022). "Other research found that class II molecules (HLA-DPA1, HLA-DPB1, HLA-DQA1, HLA-DRA, HLA-DRB1, HLA-DRB5) are important biomarkers in the occurrence and progression of melanoma tumors, and their expression levels are closely related to prognosis and immune infiltration." (PMID 39969704, 2025). "Consistent with roles of HLA-DRB1 in CD4+ T cell activation, our findings demonstrate that HLA-DRB1 is expressed and fucosylated in melanoma and required for l-fuc-triggered CD4+ T cell-mediated itIC induction and melanoma suppression." (PMID 36690875, 2023). "We also compared HLA-DRB1*04 frequencies in participants with melanoma who reported "Celtic" and "non-Celtic" ancestry." (PMID 15310399, 2004). "In applying this technique further to formalin-fixed, paraffin-embedded (FFPE) melanoma tissue specimens, we observed similar staining patterns for fucosylated HLA-DRB1, which were completely abolished by washing the tissue with l-fuc, confirming specificity for fucosylated HLA-DRB1." (PMID 36690875, 2023).
melanoma (continued). "In contrast, melanoma cells lines expressing HLA-DRB1*0301 while lacking TRP-1, like Ma-Mel-103b as well as HLA-DRB1*0301− melanoma cell lines expressing TRP-1, such as Ma-Mel-153, were ignored." (PMID 21152437, 2010). "Finally, immunoprecipitation and IB analysis of V5-tagged HLA-A or HLA-DRB1 revealed direct recognition of HLA-DRB1 by AAL, indicating that a fraction of total HLA-DRB1 but not HLA-A is directly fucosylated in melanoma." (PMID 36690875, 2023).